AR (androgen receptor)
Diseases named in the same sentence as AR in open-access papers (continued):
Sharing a sentence is not in itself a finding about the gene and the disease.
breast carcinoma (continued). "Our previous studies demonstrate that these important drug targets in breast cancer, ESR1, PGR, HER2, EGFR, and AR have a high similarity in mRNA and protein variations in both tumors and cell lines." (PMID 36360219, 2022). "AR is expressed in 10–63% of TNBC, and its expression is correlated with good prognosis in early-stage breast cancer in terms of both disease-free survival (DFS) and overall survival (OS)." (PMID 35329934, 2022). "In this study, we investigated the relationship between AR expression and treatment response in HER2-positive breast cancer patients treated with HP neoadjuvant therapy." (PMID 35207749, 2022). "The AR can be expressed in both ER+ and ER− BRCA and its role in driving breast cancer growth depends on ER co-expression." (PMID 36171192, 2022). "We found that the levels of AR were higher in cancer tissues than that in para-cancerous tissues at Luminal A, Luminal B, and HER2-positive breast cancer, while it was the exact opposite in TNBC." (PMID 35880165, 2022). "There is increasing evidence of unique molecular profiles and targetable pathways other than AR signaling in QNBC versus TNBC and other breast cancer subtypes." (PMID 35203574, 2022). "Investigation of miRNA profiles, regulatory networks and pathway analysis of these networks in QNBC compared with AR+ TNBC and other breast cancer subtypes has been sparse so far." (PMID 35203574, 2022). "MDA-MB-453 LAR-type breast cancer cells are highly sensitive to CDK4/6 inhibitors, and enzalutamide enhances the efficacy of palbociclib in AR-positive/RB-proficient TNBC cells." (PMID 37435447, 2022). "Since a similar pro-tumorigenic role of AR has also been observed in ERα-/HER2-positive (HER2+) breast cancers, AR blockage has been proposed as an effective treatment strategy in ERα- breast cancer." (PMID 35008851, 2021). "Previous studies identified breast development and metastasis pathways of androgen-androgen receptor/KDM1A target genes, and androgen-AR was identified as an oncogenic factor with epigenetic mechanisms involved in breast cancer carcinogenesis." (PMID 33799951, 2021). "AR (NR3C4) is essential for the development of male reproductive organs, and it is also expressed in the majority of breast cancers." (PMID 34638457, 2021). "A previous study with human breast cancer MCF-7 cells showed that PFHxS is a weak agonist of estrogen receptors (ESR1) and a potential weak antagonist of the androgen receptor (AR)." (PMID 34706750, 2021). "Thus, AR inhibitors may be effective in endocrine-resistant luminal breast cancer." (PMID 34680352, 2021). "Despite these data and the established role of FOXA1 in governing ER and AR transcriptional programs, little is known regarding the impact of FOXA1 on GR target genes in this breast cancer subtype." (PMID 34680352, 2021). "Cotreatment of the AR antagonist enzalutamide and IU1 downregulates AR and inhibits AR-related signaling pathways in breast cancer." (PMID 34575114, 2021). "The high AR expression was a significant independent prognostic factor that correlated to improved OS and DFS of breast cancer patients." (PMID 34490107, 2021). "As proof of principle, we performed genome editing of specific amino acids within the pioneer transcription factor FOXA1, a critical component of estrogen and androgen receptor signaling, in MCF‐7 breast cancer cells." (PMID 33666335, 2021). "Here we provide an in-depth account of the critical roles of CBP/p300 in regulating the AR and ER signaling pathways and discuss the potential of CBP/p300 inhibitors for treating prostate and breast cancer." (PMID 34201346, 2021).
breast carcinoma (continued). "In breast cancer, it was found that RUNX2 functioned through the androgen receptor to regulate prolactin-induced protein (PIP), a new biomarker for keratoconus." (PMID 34233613, 2021). "In some salivary duct carcinomas, like breast cancers, the expressions of androgen receptor (AR) or human epidermal growth factor 2 (HER2) were observed to be positive, and AR-targeted hormonal therapy and a HER2-targeted antibody showed high response rates." (PMID 35006440, 2021). "Androgen receptor-targeted therapies, including androgen receptor agonists, androgen receptor antagonists, and PI3K inhibitors, have shown encouraging outcomes in breast cancer clinical trials." (PMID 34722557, 2021). "Androgen receptor (AR) expression is observed in up to 86% of HER2+ breast cancers and has been investigated as a potential therapeutic target in breast cancer." (PMID 33591468, 2021). "Altogether, our results indicate that BC-N102 exhibited its therapeutic effect via suppression of PR and AR signaling while mediating the activation of MR signaling irrespective of the presence or absence of the receptor's ligand in the breast cancer cell line." (PMID 34421361, 2021). "AR-positive TNBC, referred to as molecular apocrine breast cancer, typically arises in older women and has a relatively better prognosis than AR-negative TNBC." (PMID 32697770, 2020). "This comprehensive dataset included many established biomarkers for breast cancer, including the receptor tyrosine kinase erbB-2 (HER2), estrogen receptor (ESR1), progesterone receptor (PGR), and androgen receptor (AR)." (PMID 32489334, 2020). "The AR-targeting ARV-110 and ER-targeting ARV-471 (Arvinas) are currently undergoing recruitment for phase I clinical trials against prostate and breast cancer, respectively (NCT03888612/NCT04072952)." (PMID 33324551, 2020). "The prognostic impact of AR has been reported to be closely related to the ER, the progesterone receptor (PR), and the human epidermal growth factor receptor 2 (HER2) in breast cancer." (PMID 32290220, 2020). "The two breast cancer cases classified as ERa+ (BC1 and BC3) co-expressed abundant PR and AR in the same cell." (PMID 33266334, 2020). "There are opposing findings when comparing AR and PTEN transcript expression in prostate verses breast cancer." (PMID 33062889, 2020). "Interestingly, recent studies shown that androgen receptor expression inversely correlates with immune cell infiltration in breast cancer, and low level of DHT could promote the infiltration of CD8+ T cells in prostate of benign prostatic hyperplasia (BPH) tissues." (PMID 32514254, 2020). "Other studies have described interactions between other nuclear receptors such as PR, AR and LRH-1, capable of interacting with ERα in breast cancer." (PMID 32168782, 2020). "In ER+ breast cancer models, DHT-mediated activation of AR has been shown to inhibit ERα signaling and cell cycle progression through a reduction in cyclin D1 transcription." (PMID 33062889, 2020). "STP analysis enabled calculation of an AR over ER pathway activity ratio instead of the AR over ER protein expression ratio, revealing a relatively low ratio in luminal A/B and a high ratio in higher grade HER2 and basal breast cancer subtypes." (PMID 33613616, 2020). "In HPA’s breast cancer cases, TRPM4 and AR protein was expressed in 90.9% (n = 10/11) and 100% (n = 12/12) of the cases, respectively." (PMID 32484822, 2020). "To explore the relationship between USP14 and AR, we analyzed the expression levels of USP14 in AR positive breast cancer." (PMID 31126320, 2019).
breast carcinoma (continued). "Anti-androgen therapies are under investigation for breast cancer in different settings and phase II studies in metastatic TNBC AR+ patients have already obtained encouraging results." (PMID 31245286, 2019). "Contrarily, in the breast cancer cell lines MCF-7 and SK-BR-3 the AR was shown to downregulate miR-21 expression, primarily by recruiting HDAC3 to the miR-21 promoter." (PMID 31744106, 2019). "Although CDK4/6 inhibitors have a great tendency to bring about positive prognosis of HR+/HER2- breast cancer patients, for other type such as HER2+, TNBC or AR+ breast cancer, the application of CDK4/6 inhibitors still needs further intensive studies." (PMID 31777590, 2019). "The majority of ER-positive breast cancers and up to 45% of TNBC express the AR in tumour tissue, making this biomarker an interesting therapeutic target." (PMID 31718606, 2019). "In the present study we provide a mechanism by which ligand-activated AR, down-regulates estrogen-dependent MCF-7 human breast cancer cell proliferation by inhibiting the ability of E2/ERα signalling to direct transcription of the cyclin D1 gene promoter." (PMID 31684907, 2019). "We evaluated AR as a prognostic and predictive marker among 3021 postmenopausal participants of the BIG 1–98 trial with early stage ER+ breast cancer." (PMID 30795773, 2019). "In both the I-SPY 1 and METABRIC datasets, we noted a lower expression of AR in TNBC than in HR+/HER2− and HER2+ disease, and the lowest expression in basal type breast cancer." (PMID 31840050, 2019). "Studies in breast cancer cell lines showed reduced proliferation and increased apoptosis in non-LAR lines when treated with the androgen antagonist enzalutamide, even when AR expression was low." (PMID 31769425, 2019). "This study investigates for the first time AR and FOXA1 expressions in a large cohort of feline invasive mammary carcinomas." (PMID 31888566, 2019). "To corroborate the findings drawn from our analysis, we performed immunohistochemical staining of a human breast cancer TMA for both SOX10 and AR." (PMID 30279965, 2018). "In molecular apocrine breast cancer, AR has been shown to directly induce HER2 expression, and AR is upregulated by HER2-stimulated ERK activity." (PMID 29382369, 2018). "AR activation induced by dihydrotestosterone (DHT) prevented cells proliferation, migration, invasion and self-renewal capacities in ER+ breast cancer cells, via transcriptional up-regulation of let-7a." (PMID 29423076, 2018). "Spine membrane localization of AR and ER may be accomplished via palmitoylation of receptors, as judged from recent studies, including the finding that some populations of ERα and ERβ were plasma membrane-bound in cultured breast cancer cells MCF-7, and they were anchored via palmitoylation." (PMID 29765299, 2018). "CR1447 (4-hydroxytestosterone, 4-OHT; NCT02067741) is an ointment that is being assessed in the treatment of ER+ve, AR+ve and HER2-ve advanced breast cancer." (PMID 30416486, 2018). "Models should not be too generic, as they should include important read-outs of cancer types such as AR for prostate or ER and BRCA1 for breast cancer allowing them to better separate cancer subgroups." (PMID 30733688, 2018). "This evidence depicts AR as a therapeutic target, potentially very exploitable, for TNBC and provides new opportunities for the treatment of this deadly kind of breast cancer." (PMID 30210453, 2018). "According to reports, over 70% of ER-positive breast cancers, approximately 60% of HER2-positive breast cancers, and 30% to 45% of TNBC (triple negative breast cancers) express AR." (PMID 30547831, 2018). "We first examined the expression of Ki67, ER, progesterone receptor (PgR), AR, and VDR and the phosphorylation of AKT Ser473 and ERα Ser167 by immunohistochemistry (IHC) in breast cancer tissues in pre- (n = 62) and postmenopausal (n = 152) women." (PMID 29707142, 2018).
breast carcinoma (continued). "Among human breast cancer cell lines, MDA-MB-453 cells express AR at high levels, and their proliferation is stimulated by androgens in an AR-dependent manner." (PMID 29713287, 2018). "In breast cancer MCF-7 cells, about 8% of the total number of ERα and AR co-immunoprecipitates under basal conditions." (PMID 30210453, 2018). "However, triptolide inhibits proteasome activity in prostate and breast cancer, indicating that the ubiquitin proteasome pathway may be not responsible for AR protein degradation caused by triptolide." (PMID 30344270, 2018). "AR is able to compete with ER for bindings at ER response elements (EREs), and transfection of MDA-MB-231 breast cancer cells with the AR DNA binding domain has been shown to inhibit ER activity." (PMID 28085048, 2017). "Discordance in estrogen receptor alpha (ERα), progesterone receptor (PR), androgen receptor (AR) and human epidermal growth factor receptor 2 (HER2) status between primary breast cancers and solid distant metastases (“conversion”) has been reported previously." (PMID 28903441, 2017). "To validate the IPA model, we measured the expression of AR, FOXA1 and GSKB3 at mRNA level in 122 out of the 131 breast cancer cases." (PMID 28345661, 2017). "In summary, we have shown for the first time that ERα, PR, AR and HER2 expression in primary breast cancers is frequently lost in peritoneal and pleural effusion metastases." (PMID 28903441, 2017). "Much of the available data on AR signaling is in triple-negative breast cancer (TNBC), which is an aggressive disease with inferior outcomes comparative to other breast cancer subtypes." (PMID 28245550, 2017). "Interestingly, in spite of differences in consensus DNA binding motifs, AR is able to bind estrogen response elements and activate a transcriptional program similar to the ER—indicating that AR may be important mediator of breast cancer cell survival as well as other ER-dependent tumors." (PMID 28085048, 2017). "AR signaling is an important oncogenic driver in several tumor types, including HNSCC, prostate and a subset of breast cancers." (PMID 28903437, 2017). "This screen, which coupled the RT response of 21 breast cancer cell (BCC) lines using clonogenic survival assays with high-throughput drug screen data, identified AR inhibition as a top target for radiosensitization." (PMID 28840192, 2017). "The Cancer Genome Atlas (TCGA) Network analyzed breast cancers using RPPA and defined a luminal tumor subtype that showed high ER, AR, and BCL2 protein expression." (PMID 29050296, 2017). "A ChIP-seq and gene microarray analysis of the ZR-75-1 luminal breast cancer cell line proved that in the presence of higher concentration of one ligand (DHT versus estradiol) over the other could lead to either an increase or decrease in the ER/AR transcriptional activity." (PMID 29254284, 2017). "AR expression has been reported in over 70% of estrogen receptor (ER)-positive (ER+) breast cancers, approximately 60% of HER2-positive (HER2+) breast cancers, and 30% to 45% of triple-negative breast cancers (TNBCs)." (PMID 28957377, 2017). "Recent discrepancies concerning the role of AR have been noted in various TNBC basic and clinical studies and both AR agonist and AR antagonist clinical trials have been designed for the treatment of TNBC and ER+ breast cancers." (PMID 28299476, 2017). "It is notable that PIP is an established transcriptional target of AR and AR activation is necessary and sufficient for PIP expression in breast cancer cells." (PMID 28915724, 2017). "This is a reflection of the fact that AR activation is necessary and sufficient for PIP expression in breast cancer cells." (PMID 28915724, 2017).
breast carcinoma (continued). "It is known that TFF3 induces the expressions of AR, FOXA1, HER2 and basic fibroblast growth factor (bFGF) in vitro in various cancers such as breast cancer and melanoma cells." (PMID 28070169, 2017). "Here we report IHC staining of ERα, PR, AR and HER2 complemented with HER2 in situ hybridization in 69 patients with primary breast carcinomas and their matched malignant peritoneal and/or pleural effusions and solid distant metastases." (PMID 28903441, 2017). "The Molecular Taxonomy of Breast Cancer International Consortium (METABRIC) dataset was able to add a clinical attribute track and when the PAM50 subtype was applied, AR and FOXA1 were mainly altered in the basal subtype." (PMID 29137314, 2017). "An exploration of the web-based genetic analysis in the present study showed that approximately 10% of breast cancers were altered in ESR1, AR, or FOXA1 genes and generally changes in genes concurrently occurred even though the frequency was low." (PMID 29137314, 2017). "Meta-analyses were conducted to study impacts of AR on DFS and OS for all breast cancer subtypes and drew contradictory results for OS." (PMID 27374089, 2016). "In breast cancer MDA-MB-231 cells, both type 3a AR and type 3b AR enhanced the activity of the TMPRSS enhancer reporter in the absence of androgen, and this activation was not affected by DHT treatment (green and yellow columns)." (PMID 28035996, 2016). "Parallel reports show that AR regulates actin cytoskeleton architecture, E-Cadherin expression, EMT, and tumor metastasis in several breast cancer cell lines." (PMID 27746764, 2016). "Nevertheless, important drug targets in breast cancer, such as ESR1, PGR, HER2, EGFR and AR possess highly correlated in mRNA-protein expression both in tumors and cell lines." (PMID 27556158, 2016). "Since AR and androgens increase the proliferation of a molecular apocrine breast cancer cell line, MDA-MB-453, it is widely perceived, albeit falsely, that AR is an unfavorable therapeutic target and prognostic marker in molecular apocrine subtype." (PMID 27918430, 2016). "These important drug targets in breast cancer, ESR1, PGR, HER2, EGFR and AR have a high similarity in mRNA and protein variation in both tumors and cell lines." (PMID 27556158, 2016). "In order to further evaluate biological functions of TACC2 in human breast carcinoma cells, we transfected specific siRNA for TACC2 in MCF‐7 (ER+ and AR+) and MDA‐MB‐453 (ER‐ and AR+) breast carcinoma cells." (PMID 27333920, 2016). "Similar to several other studies, AR expression correlated with better DFS and OS in both luminal breast cancer and TNBC." (PMID 27918430, 2016). "In this study we sought to correlate androgen receptor (AR) expression with tumor progression and disease-free survival (DFS) in breast cancer patients." (PMID 27285752, 2016). "This study also clarified that targeting AR would present an attractive treatment option for MABC cases, and these results were of help in choices for treatment in individual breast cancer patients." (PMID 27340922, 2016). "However, in this study, we could not find significant association between TACC2 status and AR LI in breast carcinoma cases or induction of TACC2 mRNA expression by DHT treatment in breast carcinoma cells." (PMID 27333920, 2016). "Considering the significance in this finding, the authors recommended that the AR be considered as one of three prognostic markers to classify breast cancers as triple-positive (ER, HER2, and AR-expressing) or triple-negative (ER, HER2, and AR-negative)." (PMID 27918430, 2016). "Particularly in breast cancer tissues, positive correlations between p-ELK1 expression and AR or estrogen receptor expression were noted." (PMID 26342199, 2015). "We have previously demonstrated an inverse relationship between sex steroid receptor(s) (AR and ER) expression and ACSL4 expression in both breast cancer and PCa." (PMID 26636648, 2015).